ARMC10 (armadillo repeat containing 10)
Description:
May play a role in cell survival and cell growth.
Synonyms: SVH; PSEC0198; MGC3195; PNAS-112; PNAS112
Tractability: Antibody: UniProt predicts a signal peptide or a membrane-spanning region. PROTAC: ubiquitination databases record sites on it; its protein half-life has been measured.
Gene: Protein-coding gene on chromosome 7 (103,074,625 to 103,102,902, forward strand). Ensembl gene ENSG00000170632.
Subcellular location: Endoplasmic reticulum membrane; Mitochondrion outer membrane (Isoform 2)
Subcellular location (Human Protein Atlas): Mitochondria
Gene Ontology:
Biological process: axonal transport of mitochondrion
Cellular component: endoplasmic reticulum; mitochondrial outer membrane; mitochondrion; axon cytoplasm; endoplasmic reticulum membrane
Genetic constraint (gnomAD): Loss-of-function variants: 23 observed, 24.31 expected, observed/expected ratio (o/e) 0.95, 90% interval 0.68 to 1.34. The upper end of that interval is the gene's LOEUF score, 1.34, which puts it in group 5 of 6, group 1 being the genes least tolerant of losing a copy. Missense variants: 294 observed, 338.7 expected, observed/expected ratio (o/e) 0.87, 90% interval 0.79 to 0.96. Synonymous variants: 106 observed, 131.6 expected, observed/expected ratio (o/e) 0.81, 90% interval 0.69 to 0.95.
Homologues: Orthologues: chimpanzee ARMC10 (99% identical), macaque ARMC10 (86% identical), pig ARMC10 (73% identical), rabbit ARMC10 (73% identical), dog ARMC10 (72% identical), mouse Armc10 (71% identical), rat Armc10 (69% identical), guinea pig ARMC10 (66% identical). Paralogues in human: ARMCX3 (50% identical), ARMCX1 (48% identical), ARMCX2 (44% identical), ARMCX4 (38% identical), ARMCX5 (27% identical), ARMCX6 (25% identical), GPRASP1 (24% identical), GPRASP2 (23% identical), GPRASP3 (20% identical), ARMC12 (19% identical).
Diseases named in the same sentence as ARMC10 in open-access papers:
ARMC10 is named in the same sentence as 10 diseases in open-access papers, as found by Europe PMC text mining. Sharing a sentence is not in itself a finding about the gene and the disease. The quoted sentences say what the papers report.
breast carcinoma (1 paper, 2020). "In addition, several studies have indicated that PTPRN2 promotes the metastasis of breast cancer cells and that ARMC10 plays a crucial role in mitochondrial dynamics." (PMID 32528873, 2020).
diabetes (1 paper, 2021). "A growing number of studies have shown that mitochondrial dysfunction plays a key role in diabetes, which suggests that ARMC10 inhibits the progression of diabetes by interacting with the KIF5/Miro/Trak2 complex." (PMID 34912852, 2021). "For example, both ARMC10 and ARMCX3 interact with the Miro/Trak2 complex in mitochondria and thus regulate mitochondrial function to inhibit the progression of AD, PD, diabetes, cancers, mitochondrial diseases, immune-related diseases, and other mitochondrial-related diseases." (PMID 34912852, 2021).
glioma (1 paper, 2021). A benign or malignant brain and spinal cord tumor that arises from glial cells (astrocytes, oligodendrocytes, ependymal cells). "However, there is no additional domain other than a central armadillo repeat domain, which suggests that ARMC10 is related to myeloid tumors and gliomas through the interaction of its armadillo repeat domain with other proteins." (PMID 34912852, 2021). "For example, ARMC10 harbors potential ligand-binding pockets that may interact with TMZ, which leads to TMZ drug-resistant glioma." (PMID 34912852, 2021). "Moreover, ARMC10 interacts with TMZ to relieve the effect of TMZ and thus induces TMZ drug-resistant glioma." (PMID 34912852, 2021). "Moreover, temozolomide (TMZ)-resistant glioma cell lines are characterized by many activated functions, such as EMT, Wnt signal transduction, and the immune response, in which ARMC10 may play a key role." (PMID 34912852, 2021).
hepatocellular carcinoma (1 paper, 2021). A malignant tumor that arises from hepatocytes. "Conversely, ARMC10, which is a close phylogenetically related gene, has been found to be upregulated in hepatocellular carcinoma (HCC)." (PMID 33807672, 2021).
ischaemic stroke (1 paper, 2024). "Therefore, the aim of the present study was to investigate the role of ARMC10 through the altering mitochondrial dynamics involved in the pathological process of ischaemic stroke, thereby affecting neuronal function." (PMID 38924214, 2024). "However, there are few reports on the involvement of ARMC10 in the pathological process and mechanism of ischaemic stroke." (PMID 38924214, 2024). "Therefore, the aim of this study was to investigate the mechanism by which ARMC10 regulation of mitochondrial dynamics affects mitochondrial function involved in ischaemic stroke (IS)." (PMID 38924214, 2024). "Secondly, this study only investigated the mechanism by which ARMC10 affects mitochondrial dynamics, mitochondrial function and neuronal apoptosis in ischaemic stroke in a cellular model, but lacked the corroboration of in vivo studies." (PMID 38924214, 2024).
nervous system disorder (1 paper, 2022). A non-neoplastic or neoplastic disorder that affects the brain, spinal cord, or peripheral nerves. "On the other hand, the ARMC proteins including ARMC4, ARMC5, ARMC6, ARMC7, ARMC8, ARMC10, and ARMCX3 regulate the Wnt signaling pathway leading to specific nervous system disorders." (PMID 36553564, 2022).
ARMC10 also shares sentences with these, for which no sentence is quoted: tumor (3 papers); Alzheimer disease (1); cancer (1); mitochondrial disease (1).